BARD1 (BRCA1 associated RING domain 1)
Diseases named in the same sentence as BARD1 in open-access papers (continued):
Sharing a sentence is not in itself a finding about the gene and the disease.
breast cancer (continued). "In breast cancer, UBE2T was shown to facilitate the polyubiquitination and degradation of BRCA1—an E3 ubiquitin ligase and a critical tumor suppressor gene in hereditary breast cancer--by interacting with the BRCA1/BRCA1-associated RING domain protein (BARD1) complex." (PMID 34257599, 2021). "Mutations in BARD1 confer an increase in the risk for breast cancer, but it is not studied whether or not they predispose to prostate cancer." (PMID 34771627, 2021). "The latest reports show though that deleterious BARD1 variants may be the reason for hereditary breast cancer in BRCA1 and BRCA2 negative families." (PMID 33114377, 2020). "Further research on the BARD1 gene expression may contribute to the effective reversal of PARPi resistance and the wider introduction of new targeted therapies for the treatment of breast cancer patients." (PMID 33114377, 2020). "Interestingly, we found that about 10% of our breast cancer specimens had low nuclear BARD1." (PMID 33024116, 2020). "Additionally, nuclear COMMD1 was suggested to participate in the cellular response to DNA damage, through its ability to interact with the DNA repair proteins Breast Cancer 1 Early Onset (BRCA1), BRCA1-associated RING domain protein 1 (BARD1) and Checkpoint kinase 2 (Chk2)." (PMID 27788210, 2016). "MSH3 also directly and indirectly interacts with breast cancer susceptibility gene product (BRCA1) and BRCA1-associated RING domain protein 1 (BARD1) which may partially provide an explanation for the background of gynecological and CRC in both Lynch syndrome and BRCA1 individuals." (PMID 23209772, 2012). "Expression of BARD1 and BRCA1 are upregulated by activation of the PI3K/Akt pathway in these resistant breast cancer cells." (PMID 39858015, 2025). "In breast cancer, tamoxifen-resistant cell lines express significantly higher levels of both BRCA1 and BARD1, diminishing the cytotoxic impact of chemotherapy." (PMID 41009605, 2025). "For example, for breast cancer, international guidelines now classify genes as high (BRCA1/2), moderate (BARD1), and low penetrance (BRIP1) and favor mastectomy for high penetrance but surveillance with magnetic resonance imaging and mammograms for others." (PMID 40282361, 2025). "In this study, we describe new mouse models, based on Brca1-def and Bard1-def orthotopic allografts, that recapitulate the clinical response and progression phases of PARPi therapy observed in BRCA1/2-mutant breast cancer patients." (PMID 38956205, 2024). "Furthermore, another group of researchers using DHPLC analysis of 210 breast cancer families (129 families have no mutations in BRCA1 or BRCA2) of Australian ethnicity have identified a set of nine coding mutations of BARD1 including two novel variants (Thr598Ile and Ile692Thr)." (PMID 35650591, 2022). "Finally, the BARD1 gene could offer a new avenue for advancing the field of breast cancer therapy." (PMID 35650591, 2022). "Based on Structural and functional analysis of BARD1 gene as well as evidence from literature and bioinformatics database we concluded the BARD1 gene might potentially harbor a substantial engagement in breast cancer development and progression based on the presenting varient/s." (PMID 35650591, 2022). "Missense mutations in BRCA1 (e.g., p.Cys61Gly) has been shown to be capable of distracting the BARD1/BRCA1 interaction, thus leading to breast cancer." (PMID 30975222, 2019). "In this study, we found that BARD1 and BRCA1 were highly expressed in tamoxifen-resistant breast cancer cells, which led to enhanced DNA damage repair and resistance to DNA-damaging chemotherapy." (PMID 29686231, 2018). "For example, several sex-ratio genes were found to interact with brc-1 and brd-1, the orthologs of the human breast cancer genes BRCA1 and BARD1, respectively." (PMID 28506208, 2017). "However, it does not deny the role of BARD1 as the breast cancer susceptibility gene." (PMID 25994375, 2015).
breast cancer (continued). "Breast cancer (BC) risk is significantly associated with pathogenic variants in at least eight susceptibility genes: BRCA1 (MIM#113705), BRCA2 (MIM#600185), PALB2 (MIM#610355), ATM (MIM#607585), CHEK2 (MIM# 604373), BARD1 (MIM#601593), RAD51C (MIM#602774), and RAD51D (MIM#602954)." (PMID 41230741, 2026). "As enrichment of both DCAF8L1 and DCAF8L2 is observed in certain human breast cancer cells, these factors may promote carcinogenesis via negative regulation of BRCA1 and BARD1." (PMID 41009605, 2025). "HRD extends beyond BRCA1/BRCA2 mutations to include non-BRCA genes (RAD51C/RAD51D, BRIP1, BARD1, ATM, PALB2), broadening actionable targets across ovarian and breast cancer subtypes, including HER2-positive (30–40%) and luminal subtypes (15–25%)." (PMID 40864792, 2025). "Unlike BRCA1/2 mutation carriers, bilateral breast cancer was not commonly seen in BARD1 mutation carriers, while 29.8% of the BRCA1 and BRCA2 mutation carriers developed bilateral breast cancers (p-value = 0.039)." (PMID 40805222, 2025). "No PGVs were seen in the breast cancer susceptibility genes RAD51C, RAD51D, or BARD1, all of which are known to be associated with triple-negative breast cancer, although not all patients had multigene panel tests including these genes." (PMID 39964682, 2025). "Two recent large case control studies CARRIERS in the USA3 and BRIDGES mainly in Europe4 identified six additional genes with actionable increased risks of breast cancer with ORs of around twofold to threefold (RAD51C, RAD51D, BARD1, ATM, CHEK2) and one at fourfold to fivefold (PALB2)." (PMID 38609177, 2024). "Moreover, next-generation sequencing revealed that beyond BRCA1/2, mutations in homologous recombination effectors, such as PALB2, RAD51, ATM, BRIP1, BARD1, and CHEK2 also occur in breast cancer." (PMID 36613148, 2023). "Using the breast cancer study as an example, it was found that the known eight famous genes—BRCA1, BRCA2, PALB2, BARD1, RAD51C, RAD51D, and ATM—in breast cancer research and practice actually lead to very low accuracy in predicting breast cancer status at the stage of diagnosis." (PMID 36298522, 2022). "BARD1, RAD51C and RAD51D explain 0.31% of the breast cancer polygenic variance." (PMID 36162851, 2022). "For example, in mice, inactivation of the Bard1 protein induces mammary tumors that are indistinguishable from tumors that result from Brca1 knock-out." (PMID 32997669, 2020). "Comparisons with non-cancer east-Asian populations and European familial breast cancer cohorts revealed significant enrichment of PALB2, BARD1, and BLM mutations." (PMID 32566746, 2020). "Neoadjuvant chemotherapy offers opportunity to assess the molecular changes of heterogenic breast cancer tissue before and after chemotherapy, especially in the case of TNBC, in which BARD1 gene deleterious alterations are the most prevalent and NACT seem to have the greatest value." (PMID 33114377, 2020). "Moreover, BARD1 and BRCA1 were positively correlated with p-AKT expression in primary and metastatic breast cancer samples, suggesting that BARD1/BRCA1 expression is associated with PI3K pathway activation." (PMID 29686231, 2018). "IHC staining showed that the expression of BARD1 and BRCA1 was significantly increased in the recurrent tamoxifen-resistant tumors than that in primary tumors, in agreement with the finding of upregulated BARD1 and BRCA1 in tamoxifen-resistant breast cancer cell lines." (PMID 29686231, 2018).
breast cancer (continued). "BARD1 mutations are expected to account for additional cases of non-BRCA1/2 inherited breast cancer and have been reported in non-BRCA mutated breast cancer families." (PMID 29292755, 2017). "Conditional inactivation of Bard1 in mice induces mammary carcinomas that are indistinguishable from carcinomas induced by conditional knock-out of Brca1, which establishes BARD1 itself as a tumor suppressor." (PMID 29292755, 2017). "Nevertheless, mammary-specific inactivation of either the Brca1, Bard1, or Brca2 gene readily induces mammary tumors despite the fact that mice lacking expression of these genes also die during early embryogenesis." (PMID 27058754, 2016). "Further, in other study demonstrated that BARD1 and RAD51 are frequently overexpressed in BMs from breast cancer and may constitute a mechanism to overcome reactive oxygen species-mediated genotoxic stress in the metastatic brain." (PMID 25559688, 2015). "However, no consensus was reached for recontact regarding breast cancer risk management in intermediate penetrance CSGs (ATM, CHEK2, RAD51C, RAD51D or BARD1)." (PMID 41159931, 2025). "All of our BARD1 mutation carriers developed high-grade breast cancer, while only 44.7% of BRCA2 mutation carriers (p-value = 0.004) and 39.7% of mutation-negative patients (p-value < 0.001) developed high-grade breast cancer." (PMID 40805222, 2025). "Unlike BRCA carriers, none of the BARD1 carriers reported having bilateral breast cancer." (PMID 40805222, 2025). "In this work, we performed an in silico analysis of transcriptomic datasets in breast cancer, and focused on those involved in DNA damage, as were clearly upregulated using gene set enrichment analyses (GSEA), particular the following pathways: ATM/ATR, BARD1 and Fanconi Anemia." (PMID 33925616, 2021). "However, BARD1 and RECQL were only associated with breast cancer, without increased risk for any other diseases." (PMID 33959510, 2021). "The V695L variant shows loss of direct binding to OLA1 and decreased centrosomal localization and centrosome amplification by its overexpression; in addition, the variant fails to rescue the centrosome amplification induced by BARD1 knockdown in breast cancer cells." (PMID 32722046, 2020). "Note that the BRCA1/BARD1 ubiquitin E3 ligase generates K6 chains, and thus, palbociclib‐dependent reduction in K6 chains could be relevant for BRCA1 mutant breast cancers." (PMID 29669860, 2018). "To determine whether Vorinostat-induced BARD1 down-regulation was an exclusive event of human AML cells, we evaluated BARD1 expression levels in other human cancer models, such as MCF7 breast cancer cells, HeLa cervical cancer cells and Kelly neuroblastoma cells." (PMID 24349422, 2013). "Additional genes tested with a definite link to breast cancer included CDH1 (n=29) and BARD1 (n=19) testing negative in addition to 72 samples testing negative for BRIP1." (PMID 38609177, 2024).
ovarian carcinoma (89 papers, 2005 to 2026). A malignant neoplasm originating from the surface ovarian epithelium. "With the widespread use of multiple gene mutation screenings, numerous BARD1 pathogenic variants have been identified in breast and ovarian cancer patients to be considered for PARPi treatment." (PMID 40805222, 2025). "This study explores the prevalence of BARD1 mutations in breast and ovarian cancer among Chinese patients." (PMID 40805222, 2025). "While mutations that disrupt E3 ligase activity and stability of the BRCA1- BARD1 complex lead to a predisposition for breast and ovarian cancer, the specific requirement for E3 ligase activity in tumor suppression is not known." (PMID 36716349, 2023). "Compelling evidence have shown an association between BARD1 mutations and breast and/or ovarian cancer susceptibility; consequently, BARD1 is now included in panels of clinical genes testing for cancer susceptibility." (PMID 35650591, 2022). "Recently, an association of the BARD1 gene with ovarian cancer was suggested in the Exome Sequencing Project and Exome Aggregation Consortium for 1915 patients with a mutation frequency of 0.2% for the BARD1 gene." (PMID 35650591, 2022). "In a report on hereditary breast and ovarian cancers, two BARD1 cis mutations, P24S and R378S, were identified." (PMID 35650591, 2022). "Among women with BARD1 mutations one study appeared to show an increased ovarian cancer risk (OR 4.2 95% CI 1.4-12.5) compared to population estimates from large, publicly available exome sequencing datasets." (PMID 35159349, 2022). "Massive parallel sequencing studies have shown BARD1 loss-of-function mutation occurs in <1% of women with ovarian cancer." (PMID 35159349, 2022). "Mutations in BRCA1 and the BRCA1-associated ring domain protein (BARD1) make carriers more likely to develop breast and ovarian cancers." (PMID 36104717, 2022). "For this reason, BARD1 has been regarded as a potential breast and/or ovarian cancer predisposing gene and its association with cancer risk has been deeply investigated (reviewed in5)." (PMID 34824355, 2021). "Future studies aimed at screening larger cohorts and refining the classification of BARD1 variants will help to elucidate its role as a breast and/or ovarian cancer gene as well as define medical recommendations for BARD1 PV carriers." (PMID 33498765, 2021). "Case–control studies have shown an association of BARD1 with hereditary breast and/or ovarian cancer (HBOC) predisposition." (PMID 34824355, 2021). "The BARD1-CA125 tests proved to be specifically sensitive for the detection of ovarian cancer in women with BRCA1/2 or BARD1 mutations." (PMID 34201956, 2021). "Here, in a study of a family with hereditary breast and ovarian cancer, we find that two BARD1 mutations, P24S and R378S, simultaneously exist in cis in surviving cancer patients." (PMID 33623049, 2021). "Taken together, there is still insufficient evidence to elucidate the role of BARD1 in breast and/or ovarian cancer predisposition." (PMID 33498765, 2021). "Here, we review studies of BARD1 as a cancer predisposing gene and illustrate the challenge of discovering additional cancer risk genes for hereditary breast and/or ovarian cancer." (PMID 32726901, 2020). "A germline mutation in BARD1, Q564H, has been reported to be associated with ovarian cancer, as well as breast and endometrial cancer." (PMID 31366178, 2019). "Truncated BARD1 variants have been identified in breast and ovarian cancers and germline variants in the BARD1 gene are associated with increased cancer risk." (PMID 30925164, 2019). "The interaction of BARD1 to BRCA1 is mediated by their respective RING domains leading to the proposal that BARD1 is a candidate breast and ovarian cancer predisposing gene." (PMID 31803232, 2019). "Due to their role in BRCA1/BRCA2 DNA repair pathway, the loss-of-function mutations of RAD51C, RAD51D, BRIP1, and BARD1 genes have been generally considered as ovarian cancer susceptibility genes." (PMID 31366178, 2019).
ovarian carcinoma (continued). "Both BRCA1 and BARD1 are tested on clinical gene panels for breast and ovarian cancer susceptibility." (PMID 30925164, 2019). "In BARD1, three point mutations have been found in breast and/or ovarian cancer susceptible patients." (PMID 30857266, 2019). "Similar to BRCA1 mutations, BARD1 mutations also lead to increased risk of triple negative breast cancer and ovarian cancer." (PMID 29686231, 2018). "Exon and intron sequencing of the BARD1 gene has identified mutations in exons and introns that affect splicing in breast and ovarian cancer." (PMID 26415510, 2015). "A multigene germline mutation analysis of ovarian cancer patients at the University of Washington revealed that 18% of patients carried pathogenic mutations in susceptibility genes and that PALB2 and BARD1 were significantly associated with the occurrence of ovarian cancer." (PMID 38817903, 2024). "Importantly, the BARD1-CA125 261-sample-fitted model reached a sensitivity of 0.99 for the no-mutation (wt) and “other” groups (other than BRCA1/2 or BARD1 group of OC) and a sensitivity of 1 for the ovarian cancers with BRCA1/2 or BARD1 mutations." (PMID 34201956, 2021). "Given the lack of BARD1 loss of function mutations identified in the TCGA ovarian cancer cohort, our results indicate that BARD1 may play a more significant role in the development of ovarian cancer than previously recognized." (PMID 34680387, 2021). "The BARD1 gene is a low-risk predisposition gene for breast/ovarian cancer in its own right." (PMID 34201956, 2021). "In the present study, we have investigated the prevalence of deleterious germline BARD1 variants in a cohort of 4015 patients with clinical suspicion of hereditary breast and/or ovarian cancer, with the aim of elucidating the role of BARD1 in cancer predisposition in the Spanish population." (PMID 33498765, 2021). "Interestingly, this analysis identified only BARD1 as being potentially associated with breast and ovarian cancers." (PMID 33623049, 2021). "Mutations in the BARD1 gene have been identified as risk factors in breast and ovarian cancers." (PMID 33623049, 2021). "Risk of breast or ovarian cancer associated with potentially pathogenic BARD1 variants." (PMID 32726901, 2020). "Additionally, the recent conference report of the German Consortium for Hereditary Breast and Ovarian Cancer revealed the p.Q564X mutation in 6 out of 14 BARD1 mutation carriers in Germany." (PMID 31142030, 2019). "BARD1 SNPs and mutations that affect splicing were also reported for breast and ovarian cancers." (PMID 28030839, 2017). "Thus, most of the published data are consistent with BARD1 involvement in breast and ovarian cancers susceptibility." (PMID 29292755, 2017). "We investigated the mechanism that leads to proliferation arrest and found that BARD1δ overexpression induced mitotic arrest with chromosome and telomere aberrations in cell cultures, in transgenic mice, and in cells from human breast and ovarian cancer patients with BARD1 mutations." (PMID 28030839, 2017). "Therefore, to unequivocally elucidate this issue, we performed a comprehensive analysis of the large mutations in BARD1 in over 800 samples with either familial breast cancer or unselected ovarian cancer." (PMID 25994375, 2015). "This study suggested that deleterious mutations in BARD1 might be responsible for a certain proportion of familial breast and/or ovarian cancer." (PMID 26075229, 2015). "BARD1 may also be the target of oncogenic mutations in breast or ovarian cancer and is also important for DNA repair." (PMID 23889843, 2013). "Studies of BARD1 mutation and ovarian cancer risk are contradictory and the link remains unclear." (PMID 35159349, 2022). "Consequently, BARD1 was considered a potential candidate susceptibility gene for ovarian cancer." (PMID 33086730, 2020).